TLR4 (toll like receptor 4)
Diseases named in the same sentence as TLR4 in open-access papers (continued):
Sharing a sentence is not in itself a finding about the gene and the disease.
epilepsy (continued). "A link between TLR-4, NF-κB, and P-gp expression was also observed, determining the function of miR-542-3p in a rat epilepsy model, where this particular miRNA was shown to modify TLR-4 expression." (PMID 35890272, 2022). "The expression of TLR4 and NF-κB was highest in rats in the epilepsy group and was significantly different from that in rats in the control, EP+BAY and EP+TAK groups." (PMID 35493845, 2022). "To better evaluate the contribution of GABAARα1 and TLR4 expression patterns to epilepsy–migraine comorbidity, we used the LiCl-pilocarpine rat epilepsy model combined with inflammatory soup to establish the comorbidity rat model." (PMID 36358363, 2022). "HMGB1 is mainly involved in the pathophysiology of epilepsy by interacting with the primary receptor TLR4." (PMID 35837232, 2022). "We reported that the vulnerability involved in epilepsy–migraine comorbidity was related to the GABAARα1 subunit in distinct brain sites, and a pathway regulated by GABAARα1 included TLR4 in different brain regions." (PMID 36358363, 2022). "For the first time, we investigated the downstream role of the innate immune receptor TLR4 in GABAARα1 and combined with the epilepsy–migraine comorbidity, providing a meaningful research direction." (PMID 36358363, 2022). "(-)-Epigallocatechin-3-Gallate (EGCG) plays a therapeutic role in lithium-pilocarpine-induced epilepsy through the inhibition of the Toll-like receptor 4 (TLR4)/nuclear factor-κB (NF-κB) signaling pathway." (PMID 33746751, 2021). "Some studies have shown that intrahippocampal application of a TLR4 antagonist could reduce seizure susceptibility in mice and exert neuroprotective and anti-inflammatory effects on a seizure model, indicating that inflammation is an important therapeutic target to improve the prognosis of epilepsy." (PMID 34421582, 2021). "VX-765 and TLR4 antagonist therapy on the IL-1R1/TLR-4 signaling pathway effectively prevented the epilepsy progression and significantly reduced the chronic seizures." (PMID 34122298, 2021). "Similar pathways, mediated via HMGB1, RAGE, and TLR4 were shown to be upregulated in epilepsy animal models and surgical resections of epilepsy patients." (PMID 34966269, 2021). "This investigation supports that the HMGB1/TLR-4 axis is contributing toward seizure mechanisms during epilepsy." (PMID 34354662, 2021). "This statement is attributed to the fact that there was an increased level of HMGB1 and TLR4 in both experimental epilepsy and epileptic brain samples from the human." (PMID 33732146, 2020). "It was recently confirmed that the expression of TLR‐4 signaling cascade including HMGB1 was higher in the brain tissue of dogs with epilepsy than in normal dogs." (PMID 33150666, 2020). "Western blot analysis revealed that the epilepsy model rats exhibited higher protein level of TLR4 and phosphorylation of IκB-α and NF-κΒ p65 when compared with the control group, indicating activation of TLR4/NF-κB pathway." (PMID 32206297, 2020). "The analysis revealed an overexpression of Toll-like receptor-4 in the CA3 region of dogs with structural epilepsy." (PMID 31959173, 2020). "There is an activation of the TLR4/NF-κB signaling axis in epilepsy as evident by an upregulated expression of TLR4 and NF-κB in epileptic animals and inhibiting the TLR4 and NF-κB represent a promising strategy against epileptic seizure." (PMID 33732146, 2020). "The intensity of TLR4 expression in animals with epilepsy was only altered in the CA3 sub-region of the hippocampus of dogs with structural epilepsy." (PMID 31959173, 2020). "In conclusion, expression analysis of TLR4 and its ligands revealed complex changes, which differ between epilepsy types in canine patients." (PMID 31959173, 2020). "These animal experiments and clinical studies suggested that both HMGB1 and TLR4 expressions are upregulated in epilepsy cases." (PMID 31241711, 2019).
epilepsy (continued). "Expressions of both HMGB1 (6.3, 4.4−7.8 ng/mL vs 1.9, 2.4−3.3 ng/mL, P<0.001) and TLR4 (3.0, 2.3−3.6 ng/mL vs 0.9, 1.3−1.7 ng/mL, P<0.001) in epilepsy patients were greatly elevated compared with HCs." (PMID 31241711, 2019). "ES of the ear is effective in treating KA-induced epilepsy seizure by regulating TLR4 and related pathways in the rat brain." (PMID 29682548, 2018). "In epilepsy, analyses of hippocampal specimens obtained at surgery from patients with drug-resistant temporal lobe epilepsy showed increased TLR4 and HMGB1 expression in glial cells (astrocytes) and neurons." (PMID 27293318, 2016). "A recent study found that TLR4 activation by high-mobility group box-1 (HMGB-1, a well-known TLR4 endogenous ligand) is involved is seizures, while another study found that neuronal KC is significantly increased during epilepsy in the rat." (PMID 23034047, 2012). "HMGB1 is highly expressed in human epileptogenic brain, and antagonists of HMGB1 and TLR4 have been demonstrated to retard seizure precipitation and to decrease acute and chronic seizure recurrence in epilepsy animals." (PMID 21989210, 2011). "Interventional investigations on the IL-1β/IL-1R1/IL-1Ra and HMGB1/TLR4 pathways showed antiseizure effects, suggesting that these pathways could be therapeutic targets for epilepsy." (PMID 41155637, 2025). "Moreover, experimental epilepsy models demonstrated that blockade of either HMGB1 or genetic deletion of TLR4 using neutralizing antibodies significantly reduced seizure incidence, thereby validating the pathogenic role of the HMGB1/TLR4 pathway in epilepsy." (PMID 41306289, 2025). "In addition to glioma tissues, we observed significantly higher expression of TLR2 and TLR4 in epilepsy-derived tissues than in LGGs." (PMID 40809181, 2025). "Our objective was to compare early treatment of the pilocarpine epilepsy model through TLR4 inhibition with late treatment by evaluating pro-inflammatory agents, apoptotic expression, neuronal death in hippocampal tissue, and mortality rates in rats under both early and late treatment conditions." (PMID 40718441, 2025). "They suggested that downregulating the TLR4/NF-κB inflammatory pathway may have antiepileptic effects in epilepsy." (PMID 40718441, 2025). "In the pilocarpine-induced rat model of epilepsy, the downregulation of the TLR4/NF-kB inflammatory pathway in epilepsy inhibited microglial activation and the expression of the inflammatory factor CD6, which reflects the strong phagocytic ability of microglia." (PMID 39851521, 2025). "Experimental and clinical studies suggest that the HMGB1/TLR4 pathway is involved in epileptogenesis induced by neuroimmune inflammatory responses and contributes to the neuroinflammatory response of brain injury after epilepsy." (PMID 39046369, 2024). "Upregulation of Toll-like receptor 4 (TLR4) in the hippocampus has been observed, with its activation leading to increased influx of Ca2+ through the NMDA receptor, thereby elevating the risk of epilepsy." (PMID 38999445, 2024). "In our study, the TLR4 gene expression level was higher in the epilepsy group." (PMID 39046369, 2024). "It is suggested that HMGB1 and TLR4 expression levels correlate with epilepsy severity." (PMID 39046369, 2024). "However, the group with the highest activation of the HMGB1/TLR4/RAGE/NF‐κB pathway was the epilepsy group in this study." (PMID 39046369, 2024). "TLR4 signalling in the brain directs autoimmune responses and initiates neuroinflammation, which plays an important role in several brain disorders (e.g. cerebrovascular disease, brain tumours and epilepsy)." (PMID 39046369, 2024). "TLR4 inhibitors can effectively improve the symptoms of epilepsy in mice." (PMID 39605791, 2024). "This study aims to investigate the relationship between toxoplasmosis and this pathway, which may be effective in the formation of epilepsy by acting through the HMGB1/RAGE/TLR4/NF‐κB signalling pathway in patients with idiopathic epilepsy." (PMID 39046369, 2024).
epilepsy (continued). "Additionally, in animal experiments, targeting TLR4-related pathways has shown promise in influencing the onset and progression of epilepsy." (PMID 37946105, 2023). "Modulating GABAergic/glutamatergic neurotransmission, Nrf2/HO-1, PI3K/Akt, and TLR-4/NF-B pathways might be a therapeutic strategy for epilepsy." (PMID 37445950, 2023). "In our research, M1 macrophage in the epilepsy group were higher than in the normal group, which may be the result of increased TLR4 leading to decreased M1 macrophages and affecting their ability to clear ferroptosis cells, ultimately exacerbating epilepsy." (PMID 38020614, 2023). "Overall, these findings suggest that the TLR4/NF-κB signaling pathway may have an important role in the development of epilepsy." (PMID 35647304, 2022). "Blocking of HMGB1 by regulatory axis using anti-HMGB1 mAb, reduced the TLR4 and others receptor that may involve in promote signal of epilepsy such as RAGE." (PMID 36310854, 2022). "It has been suggested that HMGB-1 and TLR4 expression levels correlate with epilepsy severity." (PMID 35837232, 2022). "Through the process, anti-HMGB1 mAb reduces the TLR4 activity and other receptors that may involve in promote signal of epilepsy such as RAGE." (PMID 36310854, 2022). "Therefore, the HMGB1/TLR4 axis plays a key role in FCD-II-related epilepsy and mesial temporal lobe epilepsy." (PMID 35837232, 2022). "TLR4 signaling in the brain drives autoimmune responses and initiates neuroinflammation, which plays an important role in a variety of brain disorders (e.g., cerebrovascular disease, brain tumors, and epilepsy)." (PMID 35837232, 2022). "We now provide evidence in primary human 3D cultures of constitutive antineurogenic signalling via the IL1-β-IL-1R and HMGB1 RAGE/TLR4 pathways and demonstrate pharmacological reversibility in tissue from patients with severe long-standing drug refectory epilepsy and memory impairments." (PMID 34548070, 2021). "Several researches showed that TLR4 could mediate autophagy, and suppressed the apoptosis and autophagy by inhibition of the TLR4/MyD88 pathway in hippocampal neurons of epilepsy mice model." (PMID 32108135, 2020). "In addition, earlier studies reported that TLR4 antagonists exert anticonvulsant effects in two different acute seizure models and a chronic epilepsy model." (PMID 31959173, 2020). "Several earlier findings have revealed an activation of TLR4/NF-κB signaling pathway in epilepsy which is evident by an increased level of TLR4 and NF-κB in epileptic animals as well as reflecting TLR4 and NF-κB inhibition as an therapeutic strategy for minimizing epileptic seizure." (PMID 32260203, 2020). "Thus, ketosis suppresses inflammatory signaling (e.g., NLRP3/TLR4/IL-1R/NF-κB) signaling pathways and proinflammatory cytokines/enzymes (e.g., IL-1β and COX-2) that are linked pathophysiologically to epilepsy and other seizure disorders." (PMID 31680801, 2019). "Furthermore, few studies investigated the effects of HMGB1 and TLR4 on drug resistance in patients with epilepsy." (PMID 31241711, 2019). "However, most of these previous studies investigating the function of HMGB1 and TLR4 in epilepsy were performed in experimental animal models or brain specimens; few clinical studies have been performed about the roles of HMGB1 and TLR4 in epilepsy patients." (PMID 31241711, 2019). "One hundred and five epilepsy patients and 100 healthy controls (HCs) were enrolled in this case-control study, and serum samples were collected from all participants to assess the HMGB1 and TLR4 expressions by enzyme-linked immunosorbent assay (ELISA)." (PMID 31241711, 2019). "The TLR-4 and RAGE inflammatory pathway is stimulated by one of the most important pro-inflammatory cytokines knows as HMGB1, which is responsible for the release of glutamate and causing hyperexcitability of the brain during epilepsy." (PMID 31057394, 2019). "TLR4 also presented a good epilepsy prediction with an AUC of 0.908 (95%CI, 0.868−0.947)." (PMID 31241711, 2019).
epilepsy (continued). "Moreover, patients with intractable epilepsy had increased TLR4 expression compared with patients with drug-responsive epilepsy (P<0.001)." (PMID 31241711, 2019). "Overall findings suggest that blocking the HMGB1/TLR4/RAGE regulatory axis may represent a novel method for treating epilepsy." (PMID 30271319, 2018). "Several reports suggest that TLR4 plays a crucial role in epilepsy." (PMID 29682548, 2018). "Targeting HMGB1/TLR4/RAGE signaling for epilepsy has gained more attention in recent years." (PMID 30271319, 2018). "TLR4 activation in neurons and astrocytes by HMGB1 proteins is a key mechanism of seizure generation and blocking TLR4 signaling using an antagonist could also reduce the severity of epilepsy." (PMID 30271319, 2018). "Therefore, timely inhibition of TLR4 may help mitigate neuroinflammation and alleviate epilepsy symptoms." (PMID 40718441, 2025). "In a population of rats with drug‐resistant epilepsy, the expression levels of various targets in the inflammatory pathway toll‐like receptor 4 (TLR4)/nuclear factor‐kappa B (NF‐κB) are upregulated, and their drug resistance may be related to inflammatory mediators with high levels of expression." (PMID 40103702, 2025). "Furthermore, activating GABARα1 suppressed TLR-4 and prevented epilepsy development." (PMID 37445950, 2023). "Moreover, activating GABAARα1 inhibited TLR4, and recovered the behavior of epilepsy and migraine." (PMID 36358363, 2022). "However, the contribution of TLR4 to the activation or sustaining of migraine, and its microglial regulation and mechanisms that are involved in epilepsy–migraine comorbidity, is unknown." (PMID 36358363, 2022). "Moreover, the TLR4/MYD88/NF-κB/NLRP3 inflammasome pathway may be an important target for epilepsy treatment." (PMID 34421582, 2021). "Thus, manipulating TLR4 and its endogenous ligands may suppress seizures, which may be a potential therapeutic strategy for epilepsy." (PMID 35069411, 2021). "Thus, convincing evidence exists that targeting of TLR4-signaling pathways might be of particular interest for management of epilepsy based on disease-modifying approaches." (PMID 31959173, 2020). "They suggested that TLR4 contributes to epilepsy and may also contribute to epileptic therapy." (PMID 29682548, 2018). "Although TLR4 is involved in pathogen recognition and activated during infections, the HMGB1-TLR4 axis might underlie chronic epilepsy in scenarios without frank immune activation or infection." (PMID 29382328, 2018). "Our research underscores the varying levels of TLR2 and TLR4 expression in gliomas and epilepsy, with TLR2 showing a significant increase in HGGs and both TLRs exhibiting marked elevation in epilepsy tissues compared to LGGs." (PMID 40809181, 2025). "These discoveries about the functions of Bax, Bcl-2, NT4, BDNF, TLR4, NF-κB, and VEGF in epilepsy highlight how critical it is to focus on these pathways in order to create successful treatment plans." (PMID 40540445, 2025). "We performed Western blot analysis to measure TLR2, TLR4, NF-κB, and TNF-α protein levels in primary human cells derived from fresh surgically resected tissue samples of patients with HGG, LGG, and epilepsy." (PMID 40809181, 2025). "These discoveries about the functions of Bax, Bcl-2, NT4, BDNF, TLR4, NF-κB, and VEGF in epilepsy highlight how critical it is to focus on these pathways to create successful treatment plans." (PMID 40540445, 2025). "IL-1R1 and TLR4 are expressed in astrocytes and BBB ECs and have been shown to be upregulated in clinical and experimental studies of epilepsy." (PMID 39206290, 2024). "Based on these results, we can state that epilepsy and T. gondii use different proteins in the HMGB1/RAGE/TLR4/NF‐κB signalling pathway." (PMID 39046369, 2024). "Glycyrrhizin exerts neuroprotective and anticonvulsant effects in epilepsy by regulating pyroptosis via the HMGB1/TLR4/NF-κB signaling pathway, offering novel insights into its potential as a DMT for epilepsy." (PMID 39834818, 2024).
epilepsy (continued). "The levels of HMGB1 and TLR4 increase in cerebral regions of patients with mesial temporal lobe epilepsy, focal cortical dysplasia type II (FCD-II) with epilepsy, or drug-refractory epilepsy, correlating with the severity of epilepsy." (PMID 38187384, 2023). "Both miR-129-5p and miR-542-3p inhibit the development of epilepsy by suppressing HMGB1 expression and inhibiting the TLR4/NF-kB signaling pathway." (PMID 35837232, 2022). "Hence, HMGB1/RAGE/TLR4 pathway may initiate the development and persistence of seizures in people and can be addressed to achieve anti-seizure results in drug-resistant epilepsies." (PMID 36310854, 2022). "Data analysis also revealed a close relationship between elevated heat shock protein 70 kilodaltons and Toll-like receptor-4 (TLR-4) genes expression and epilepsy." (PMID 36552892, 2022). "We propose that GABAARα1 binding and negatively regulating TLR4 contribute to epilepsy–migraine comorbidity; TLR4 is a critical intermediate link in epilepsy–migraine comorbidity; immune-induced neuroinflammation in microglia may be involved in migraine and epilepsy–migraine comorbidity." (PMID 36358363, 2022). "The rats were randomly divided into four groups: a control group, epilepsy group, TLR4 inhibitor group (epilepsy+TAK-242), and NF-κB antagonist group (epilepsy+BAY11–7082)." (PMID 35493845, 2022). "Future studies are needed to explore the role of TLR4 in CSD and to elucidate the potential role of inflammation-related chemokines/cytokines regulated by TLR4 in epilepsy–migraine comorbidities." (PMID 36358363, 2022). "Therapies interfering with HMGB1/TLR4, NF-κB, IL-1β, COX-2, PGE2/EP2, and TGF-β signaling pathways, and other inflammatory targets have been proposed to treat epilepsy." (PMID 34830412, 2021). "In epilepsy patients, HMGB1 is known to mediate microglia activation and pro-inflammatory cytokine production via the TLR4/NF-κB pathway." (PMID 34830412, 2021). "MicroRNA-129-5p inhibited the development of autoimmune encephalomyelitis (AE)-related epilepsy by HMGB1 expression and inhibiting the TLR4/NF-κB signaling pathway." (PMID 30271319, 2018). "Thus, HMGB1/RAGE/TLR4 signaling might contribute toward the generation and perpetuation of seizures in humans and can be successfully targeted to attain anti-convulsant effects in epilepsies which are resistant to drugs." (PMID 30271319, 2018). "The studies about the role of TLR4 in other neurodegenerative and neurological diseases, ALS and epilepsy, gave more clear results." (PMID 27293318, 2016). "Moreover, the expression of TLR4 and COX-2, which were markedly upregulated in the PBS-treated epilepsy group, was significantly reduced following L. eligens treatment." (PMID 41356796, 2026). "In epileptic lesions, downregulation of the inflammatory pathway TLR4/NF‐κB can inhibit the activation of microglia and the expression of inflammatory factor CD68, which can inhibit the occurrence and aggravation of epilepsy, and thus improve cognitive function and emotional disorder after seizure." (PMID 40103702, 2025). "Although no drugs targeting the HMGB1/TLR4 pathway for epilepsy are currently in clinical trials, many substances can target this pathway and thus exhibit anti-epileptic effects." (PMID 41155637, 2025). "The signalling pathway in epilepsy may be activated by HMGB1, TLR4 and TLR2, which is considered to increase the level of proinflammatory cytokines." (PMID 39046369, 2024). "The signalling pathway in epilepsy may be activated by HMGB1, TLR4, and TLR2, which are considered to increase the level of proinflammatory cytokines." (PMID 39046369, 2024). "After binding to TLR2, TLR4 or RAGE, HMGB1 can trigger the activation of cytokines and affect downstream inflammatory factors that play an important role in modulating neuronal excitability, which can lead to the development of epilepsy." (PMID 39046369, 2024).